IL6 (interleukin 6)
Diseases named in the same sentence as IL6 in open-access papers (continued):
Sharing a sentence is not in itself a finding about the gene and the disease.
pancreatic cancer (continued). "For pancreatic cancer, preclinical studies have found that a new curcumin synthesis derivative (CDF) can inhibit VEGF, IL-6 and tumour stem cells, thus affecting the TME of pancreatic cancer." (PMID 33722297, 2021). "Using data from a previously published pancreatic cancer dataset, all three scores were moderately correlated with log CRP and log IL-6 levels." (PMID 34915912, 2021). "This study shows that activation of the P2X7R in PSCs leads to IL-6 release into the TME and subsequent activation of STAT3 signaling in pancreatic cancer cells." (PMID 34440697, 2021). "Additionally, macrophages were shown to regulate skeletal muscle signal transducer and activator of transcription 3 (STAT3) – downstream target of IL-6 and key regulator of skeletal muscle mitochondrial homeostasis and proteostasis – during pancreatic cancer cachexia." (PMID 33364975, 2020). "EMT is well known for its pathological role in tumor invasion and metastasis, and IL-6 has been shown to induce EMT in a paracrine manner in a variety of types of carcinoma including bladder and pancreatic cancers." (PMID 32855767, 2020). "High levels of cytokines IL-1β, IL-6, IL-8, IL-10, TGF-β, and TNF-α are observed in patients with pancreatic cancer compared to healthy patients." (PMID 32174830, 2020). "Another zinc transporter, Zip4, is reported to increase interleukin 6 transcription through CREB, resulting in cell proliferation and tumour progression in pancreatic cancer cells." (PMID 33153045, 2020). "The iCAF subpopulation is detected in invasive pancreatic cancer, and iCAFs exhibit elevated expression of VIM, FAP, COL3A1, DES, IL6, and CXCL12 and reduced expression of ACTA2 (coding α-SMA)." (PMID 33333727, 2020). "This indicated that stromal IL6 mediated increased glycolysis and ECAR in pancreatic tumor cells by increased glucose uptake via glucose transporters." (PMID 33177492, 2020). "In our study, we evaluated the changes in several important pro-inflammatory cytokines in pancreatic cancer, including TNF-α, IL-6, and IL-1β." (PMID 33634030, 2020). "IL-6/STAT3 signaling pathway was demonstrated to inhibit autophagy in U937 cells, while it activated this process in pancreatic cancer cells." (PMID 31598806, 2020). "This indicated that stromal IL6, activated STAT signaling pathway to upregulate mRNA expression of both stemness genes as well as metabolic genes in pancreatic tumor cells." (PMID 33177492, 2020). "For example, IL-32α can inhibit JAK2 / STAT3 signaling pathway to inhibit IL-6-induced EMT and tumor cell invasion and metastasis in pancreatic cancer cells." (PMID 33097029, 2020). "Il6, Ccl2, Ccl7, Cxcl12, and Pgdfra are expressed in FB1 subtype fibroblasts in the normal pancreas, as well as during the progression of pancreatic cancer." (PMID 33333727, 2020). "Given the reported involvement of IL-6 in upregulation of CAIX expression in multiple previously-mentioned cancer models, it seems plausible that IL-6 signaling could also be implicated in the transcriptional regulation of CA9 in precursor lesions as well as in primary pancreatic tumors." (PMID 32707920, 2020). "Our results suggest that, even though IL-6 and LIF share STAT3 as a downstream effector, they have distinct functional roles in human pancreatic cancer cells harboring mutant KRAS." (PMID 31296870, 2019). "In pancreatic cancer, CAFs have been divided into α-SMA expressing (myCAFs) and IL6 expressing (iCAFs) CAFs." (PMID 31101063, 2019). "Correlation of VEGF production with IL-1α and IL-6 in cell lines suggests that the expression of VEGF is regulated by IL-1α and IL-6 in pancreatic cancer and in adenoma cells." (PMID 31419243, 2019). "In addition to secreting IL-6, peri-pancreatic and pancreatic adipose tissues contribute to the production of a number of inflammatory cytokines and growth factors which may drive the growth and expansion of pancreatic tumors." (PMID 29977235, 2018).
pancreatic cancer (continued). "In addition, suppression of IL-6 remarkably promoted antitumor effect of gemcitabine, indicating that the combination of shRNA targeting IL-6 with gemcitabine may provide a potential clinical approach for pancreatic cancer therapy." (PMID 29693005, 2018). "The IL-6/STAT3 pathway in PSCs, which recruits MDSCs to the pancreatic cancer microenvironment, also displays the function of promoting EMT by activating nuclear factor erythroid 2 (Nrf2)." (PMID 30060755, 2018). "Serum IL-6 concentration was significantly higher in the GBC and pancreatic cancer groups compared to the control group in one-way ANOVA + Tukey's test (p = 0.034 and p < 0.001, resp)." (PMID 29410961, 2017). "In studies with pancreatic cancer cells, hypoxia and HIF have been shown to be important in the expression of IL-6, miR-21, miR-210 and VEGF as well as the CSC-related factors: NANOG, OCT-4 and EZH2." (PMID 28611316, 2017). "IL-6 and IL-10 were significantly increased in both the HCC and GBC groups, IL-2, IL-6, IL-10, and TNF-α in the cholangiocellular carcinoma group, and IL-2, IL-6, IL-8, and TNF-α in the pancreatic cancer group." (PMID 29410961, 2017). "Our current study provides evidence that extracellular nucleosomes promote IL-6 secretion by myeloid cells, which in turn sustains STAT3 and K-Ras signaling in pancreatic cancer cells." (PMID 28374746, 2017). "IL6 induced STAT3 phosphorylation in both MiaPaCa2 and Panc01 pancreatic cancer cell lines, but only in one of the two healthy donor-derived monocytes." (PMID 27687804, 2016). "Consistent with the repressed angiogenetic potency, FH535 also significantly decreased the levels of pancreatic cancer cell–secreted pro-angiogenic VEGF, interleukin (IL)-6, IL-8, and tumor necrosis factor (TNF)-α." (PMID 27323403, 2016). "Especially, IL-6 is assumed to participate in pancreatic fibrosis by activating PSCs and regulate PSC-induced EMT and alterations in gene expression in pancreatic cancer cells." (PMID 27655706, 2016). "Our results here show that CAF secretome activates the PI3K pathway, which plays a key role in the response of pancreatic cancer cells to pro-proliferative, pro-migratory and pro-invasive of CAF-derived stimuli including IL-6." (PMID 27177087, 2016). "Previous studies have shown that the serum levels of IL-6 were elevated and negatively correlated with the therapeutic effects of GEM in patients with pancreatic cancer." (PMID 25609203, 2015). "Recently, it was reported that silencing receptor for advanced glycation end products (RAGE) or Atg5 using shRNA significantly inhibited IL-6 induced autophagy and mitochondrial STAT3 activation in pancreatic cancer cells." (PMID 24796733, 2014). "Overexpression of the MSLN gene was shown to enhance interleukin (IL)-6 signaling, and to confer resistance to tumor necrosis factor (TNF)-α mediated apoptosis in pancreatic cancer cell lines." (PMID 25118887, 2014). "Among the cytokines and growth factor assessed, several growth factors and cytokines including IL-6, IL-8, CCL11, and IP-10 are higher in patients with pancreatic cancer." (PMID 24970174, 2013). "To evaluate the effects of regulation of Stat3 activity on pancreatic cancer invasion, we performed an in vitro invasion assay using AG490 and IL-6." (PMID 20482858, 2010). "Interleukin-6 (IL-6) treatment can enhance anoikis resistance by phosphorylating STAT3, while STAT3 inhibitors like piperlongumine can induce anoikis and prevent tumor formation and metastasis in pancreatic cancer models." (PMID 41596231, 2026). "For example, HMGA2 mediated the occurrence of triple-negative breast cancer by activating the NF-kB/IL-6/IL-8/STAT3 axis; HMGA2 activated the mTOR signaling pathway to inhibit ferroptosis, thereby enhancing the death resistance of pancreatic cancer and reducing chemotherapy sensitivity." (PMID 40703517, 2025). "IL-6 and CXCL12 have been reported to delay the early diagnose of pancreatic cancer in mice." (PMID 40248695, 2025).
pancreatic cancer (continued). "IL-6 and CXCL12 have been reported to delay the early diagnose of pancreatic cancer." (PMID 40248695, 2025). "Here, we demonstrated a completely opposite outcome of IL-6 targeting, as impairing IL-6 signaling in the TME with an IL-6R blocking antibody abolished the antitumor activity of the TGFβ vaccine in a murine model of pancreatic cancer." (PMID 39653766, 2025). "CM from the pancreatic tumor organoids of cachectic patients did not affect IL-1β, IL-6, IL-8, MCP-1, or Atrogin-1 expression." (PMID 38339292, 2024). "In pancreatic cancer, CAFs near the cancer cells exhibit a myoCAF phenotype with high TGF-β-driven α-SMA expression and lower levels of IL-6 (α‐SMAhighIL‐6low), while the more peripheral CAFs have lower αSMA expression with higher levels of IL-6 (α‐SMAlowIL‐6high) consistent with iCAFs74." (PMID 40604259, 2024). "Furthermore, numerous studies have demonstrated the unusually high activation of the IL-6/JAK2/STAT3 signaling pathway in a range of malignancies, including gastric, breast, liver, colorectal (CRC), colon, ovarian (OC), lung, and pancreatic cancers." (PMID 38666938, 2024). "In addition, the IL-6/STAT3 signaling pathway can methylate the SOCS3 via DNMT1, leading to pancreatic cancer progression and metastasis." (PMID 39195299, 2024). "Combined IL-6 and CTLA-4 blockade increases T cells in pancreatic tumors." (PMID 36881480, 2023). "We found that BA could reduce the expression of IL-6 and the ratio of p-STAT3/STAT3 and p-AKT/AKT by mediating miR-365/BTG2, which may be one of the mechanisms of BA in anti-pancreatic cancer." (PMID 37415745, 2023). "What’s more, it has also been revealed that IL-6/AKT signal is inappropriately activated in several malignancies, including pancreatic cancer and gastric cancer, and its activation can enhance tumor development and resistance to some chemotherapeutic medicines." (PMID 37415745, 2023). "IL-6/gp130/STAT3 signaling also has an established role in the aggressive and metastatic phenotype of PDAC and constitutes one of the essential signaling cascades in pancreatic cancer initiation and progression." (PMID 36495330, 2023). "Likewise, in vitro stimulation of pancreatic tumor cells with IFN-γ profoundly increased tumor cell production of CXCR3-specific chemokines, even in the presence of IL-6." (PMID 36881480, 2023). "Blocking IL-6/STAT3 signaling by anti-IL-6 antibodies or STAT3 inhibitor (NSC74859) disturbed stellate cell-induced migration and expression of mesenchymal markers in pancreatic cancer cells." (PMID 35251963, 2022). "It has been demonstrated that IL-6 is instrumental for the maintenance and progression of pancreatic cancer and lack of IL-6 completely ablated cancer progression, even with activation of oncogenic Kras." (PMID 35734893, 2022). "Moreover, the three pancreatic cancer cell lines SW1990, PANC-1, and BxPC-3 showed a higher expression of IL-6 compared with its expression in the pancreatic normal cell line HPNE." (PMID 35630552, 2022). "In addition to IL6 and TGFβ, CXCR4-mediated signaling also affects pancreatic cancer treatment significantly." (PMID 35453676, 2022). "In pancreatic cancer, evidence exists for changes toward a typical pro-inflammatory cytokine expression: in tissues higher MIF, IL-8, and CXCR-4 expression and reduced HLA-DR expression, and in serum higher IL-6 and IL-10 levels." (PMID 35034144, 2022). "In pancreatic tumors, PSCs can become myofibroblast-like and express α-SMA upon activation by growth factors (TGF-β and PDGF), inflammatory cytokines (TNF-α, IL-1, IL-6, IL-8, IL-10, etc.), as well as other factors such as EMMPRIM, ET-1, Angiotensin II, SHH, and further enrich the CAF pool." (PMID 34646829, 2021).
pancreatic cancer (continued). "Pancreatic cancer metastasis is promoted by a Notch‐dependent inflammatory feedback loop that involves recruitment and activation of M2‐like tumor‐promoting macrophages and EMT via IL6/STAT3 signaling." (PMID 34459003, 2021). "However, IL-6, secreted by inflammatory PSC, plays a significant role in mediating inflammation-related malignant progression of pancreatic cancer." (PMID 34988078, 2021). "Pancreatic cancer promotes the formation of a pro-metastatic niche in the liver by secreting IL6 produced by non-cancer cells within pancreatic tumors, which activate proinflammatory STAT3 signaling in hepatocytes." (PMID 35154607, 2021). "The second aim was to elucidate whether IL-6, the well-established cytokine in PDAC tumor progression, could be our chemoattractant candidate released by PSCs and stimulating pancreatic cancer cells." (PMID 34440697, 2021). "This was consistent with a recent study which revealed that IL-6 was higher expressed in pancreatic cancer tissues with iTLS compared to those without." (PMID 34122408, 2021). "Mechanistically, SC‐derived Interleukin 6 (IL6), which was induced by co-culture with pancreatic cancer cells, augmented cancer cell migration and invasion by activating STAT3 signaling in cancer cells, while IL6 neutralization or STAT3 downregulation abrogated these effects." (PMID 32308766, 2020). "Our recent studies have shown that exogenous SDF-1 could increase CXCR4-positive pancreatic cancer invasion and EMT, and activated pancreatic cancer stellate cells could secrete SDF-1 and IL-6 to induce EMT in pancreatic cancer." (PMID 30800209, 2019). "Recent work further showed elevated IL-8 in cachectic versus non-cachectic resected and locally advanced pancreatic cancer patients, which was not the case for IL-6, IL-1β, or TNF-α." (PMID 31769424, 2019). "Neutralizing IL-6 within the coculture system led to a reduction in the ability of macrophages to upregulate CD59 expression in pancreatic cancer cells, but the result was not so remarkable." (PMID 31685825, 2019). "Other groups reported that the IL-6/JAK2 signaling pathway inhibits autophagy, via p-STAT3, which activates Bcl-2 to regulate the expression of Beclin 1 and VPS34, while in pancreatic cancer, IL-6 induces mitochondrial localization of p-STAT3 at Ser727, upregulating autophagy flux." (PMID 32565533, 2019). "We hypothesized that IL-6, secreted by TAMs, might induce the upregulation of CD59 in pancreatic cancer cells via STAT3 activation." (PMID 31685825, 2019). "IL-6 promotes the expansion of HCC stem cells, and IL-10 promotes EMT in pancreatic cancer cells." (PMID 29338742, 2018). "Similar results have been reported with pancreatic carcinoma cells adhesion to hMEC-1 stimulated with IL-6; however, as far as we are aware no published data is available investigating the effect of IL-10 on tumour cell adhesion." (PMID 29256156, 2018). "And another report demonstrated that activated interleukin-6/Stat3 signaling could induce suppressor of cytokine signaling 3 (SOCS3) methylation via DNMT1, resulting in pancreatic cancer growth and metastasis." (PMID 28360411, 2017). "Our previous study showed that Raloxifene selectively inhibits STAT3 phosphorylation induced by IL-6 in the GP130/JAK/STAT3 signaling pathway in pancreatic cancer cell-lines (PANC-1) that express GP130, but not ER." (PMID 28430601, 2017). "Accordingly, it was observed that markers of systemic inflammation (IL-6, CRP) correlated with the increased expression of ubiquitin in skeletal muscle biopsies from cachetic patients with pancreatic cancer, and this increase correlated with the degree of weight loss." (PMID 26856534, 2016). "Finally a recent study has shown higher levels of IL-6, IL-8, IL-10, and TNF-α and lower levels of IL-23 in pancreatic cancer patients compared to healthy controls." (PMID 28050120, 2016).
pancreatic cancer (continued). "We have already identified interleukin-6 as a soluble factor highly secreted by CAFs (> 1 ng secreted per 106 CAFs), but not by pancreatic cancer cells, and whose translation / secretion is inhibited by CAF treatment with SOM230." (PMID 27177087, 2016). "In our system, due to the crosstalk between adipocytes and pancreatic cancer cells, we observed an increase in STAT3 phosphorylation in Tyr-705 in cancer cells; as a consequence of IL6/STAT3 signaling pathway activation we observed in MiaPaCa2 cells an increase in WNT5a expression." (PMID 26958939, 2016). "With downregulated IL-6, pancreatic tumor cells do not undergo EMT and do not gain an invasive phenotype." (PMID 27023622, 2016). "The present results demonstrated that the Chinese herbal medicine QYHJ could inhibit pancreatic cancer cell invasion and metastasis via the suppression of cancer-related inflammation, especially the reduction of TAM-derived IL-6." (PMID 23922983, 2013). "In the present study, we showed that QYHJ reduced TAM infiltration and effectively inhibited multiple pro-inflammatory cytokines such as TNF-α and IL-6, which suggested that QYHJ could inhibit cancer-related inflammation in pancreatic cancer." (PMID 23922983, 2013). "In the present study, we used AG490 to deplete Stat3 protein in the human pancreatic cancer cell line SW1990 and IL-6 to activate Stat3 protein in the human pancreatic cancer cell line Capan-2; we then investigated the changes in cell proliferation and invasion." (PMID 20482858, 2010). "Moreover, IL4, IL6, IL8, and IL21 receptors are overexpressed on the surface of various cancer cells, including bladder, ovarian, breast, colon, head and neck, lung, and pancreatic cancer." (PMID 40886193, 2025). "In the case of advanced lesions, pro‐inflammatory cytokines like L‐1beta, IL‐5, IL‐6, IL‐8 and TNF‐alpha were elevated in high‐grade dysplasia/pancreatic cancer compared to low‐grade/moderate dysplasia group, suggesting that immune response patterns may change across the natural history of disease." (PMID 39482824, 2025). "Based on the role of MCPIP1 as a positive regulator inhibiting the IL6/JAK2/STAT3 axis, we propose that its expression may help identify patient subgroups with high IL6/JAK2/STAT3 axis activity (i.e., pancreatic cancer patients with strong metastatic potential)." (PMID 40874680, 2025). "Likewise, hypoxic pancreatic cancer cells were shown to secrete exosomal miRNA-1246 that activated the NF-κB pathway in non-tumor cells to induce the release of IL-6 and IL-8, to promote EMT of pancreatic cancer cells." (PMID 41347080, 2025). "Further research is essential to explore how circulating IL-6 levels relate to its presence in the TME, understand its immunosuppressive role, and examine the correlation between increased circulating and tumor-infiltrating neutrophils in advanced pancreatic cancer." (PMID 38672257, 2024). "Therefore, we suspect that in pancreatic cancer, knockout of CD73 may lead to the inhibition of the IL-6/JAK/STAT3 pathway, thus inhibiting tumor cell growth." (PMID 37835536, 2023). "Likewise, our transcriptomics analysis revealed an important role for NLRX1 in pancreatic cancer cells through NF-κB, AKT, MAPK, and IL-6 signaling and highlights these pathways as likely mechanisms by which NLRX1 asserts its protective qualities in Pan02 cells." (PMID 37342194, 2023). "Additionally, in pancreatic cancer cells, quercetin prevented EMT by obstructing the signal transducer and activator of transcription 3 (STAT3) signaling pathway, reversed interleukin-6 (IL-6)-induced EMT, and consequently decreased cancer cell invasion." (PMID 37446730, 2023). "Compounding this challenge, the pancreatic tumor cells themselves produce and release potent immunosuppressive agents, such as Transforming Growth Factor-beta (TGF-β), Interleukin-10 (IL-10), Interleukin-6 (IL-6), Vascular Endothelial Growth Factor (VEGF), and the Fas ligand." (PMID 37958483, 2023).